IL6 (interleukin 6)
Diseases named in the same sentence as IL6 in open-access papers (continued):
Sharing a sentence is not in itself a finding about the gene and the disease.
infection (continued). "Interestingly, pre-incubation of RSV with LL-37 was noted to limit the expression of IL-6, CCL5, and IP-10 in response to infection." (PMID 32117246, 2020). "In agreement, a significantly enhanced production of IL-6 is not detected until day 4 after infection of human lung epithelial cells with SARS-CoV." (PMID 32276453, 2020). "Similarly, we performed qRT-PCR analysis of proinflammatory cytokines (Tnf, Il6, and Cxcl2) in both SIRT3 WT and SIRT3 KO BMDMs or PMs, which were pretreated with 3-TYP prior to Mabc-R infection." (PMID 32835604, 2020). "CRP is a nonspecific acute-phase protein induced by IL-6 and a sensitive biomarker of inflammation and infection." (PMID 33031060, 2020). "In animal models, blockade of IL-6 trans-signaling does not alter the IL-6 dependent response to infection." (PMID 32765502, 2020). "However, impaired expression of CD-associated genes ATG16L1 or IRGM in THP-1 macrophages and NOD2 in NOD2−/− murine peritoneal macrophages led to an increased AIEC intracellular replication and to the secretion of IL-6 and TNF-α upon AIEC LF82 infection." (PMID 32466328, 2020). "Sixty-two percent of patients developed an infection, which did not alter the profile of immune response, except from higher IL-6 levels at T2." (PMID 32377009, 2020). "MAP is known to upregulate IL-6, IL-23, IL-1β, and TGF-β mRNA expression as early as 1 h post-infection in MAP-infected MDMs, indicating that the development of Th17 cells may be promoted by the local cytokine environment near sites of MAP infection." (PMID 32258066, 2020). "In contrast, transcripts for other cytokines known to be secreted during DC maturation (tnf, il6) and after inflammasome activation (il1β, il18) were down modulated during infection, in accordance to the absence of secretion of these cytokines." (PMID 32582184, 2020). "Both hantavirus species failed to induce NF-kB driven transcripts, such as IL-6 and IL-1β within 48 h of infection." (PMID 32596167, 2020). "DC isolated early after infection of pigs with either of the two CSFV strains showed prominent upregulation of CCL5, CXCL9, CXCL10, CXCL11, and XCL1, as well as of the cytokines TNFSF13B, IL6, IL7, IL12B, IL15, IL27." (PMID 32733474, 2020). "The inflammatory cytokines commonly used to treat infection are WBCs, CRP, PCT, and IL-6." (PMID 32864930, 2020). "They demonstrated that neonates can cope with perinatal stress or intrauterine inflammation (elevated IL-6 values) without developing any clinical signs of inflammation or infection." (PMID 32793528, 2020). "IL-6 was increased in WT mice at day 14 post-infection, while, in EO- mice, these differences were not detectable." (PMID 33212993, 2020). "The Th17 response-related pathways (IL-6 Signaling, IL-23 Signaling Pathway, Role of IL-17F in Allergic Inflammatory Airway Diseases, Th17 Activation Pathway, LXR/RXR Activation, and PPAR Signaling) were commonly expressed at all infection times." (PMID 33520738, 2020). "After 72 h of infection, the IL-6 level remained stable between the positive and negative control groups and was similar between the colistin and SB203580 + colistin groups, but was significantly lower compared with the positive control group." (PMID 33551807, 2020). "In response to infection of mouse BMDCs and D2SC (mouse DC cell line) cells with L. monocytogenes and HSV-1, respectively, DDX41 mediated type I IFN, ISG, and pro-inflammatory cytokine (IL-6, TNFα) production in a STING-dependent manner." (PMID 32012730, 2020). "In support of this notion, in a mouse model of infection with non-typeable haemophilus influenzae, the aspirin triggered RvD1 decreased the concentration of pulmonary TNFα and IL-6 in addition to driving the clearance of macrophages." (PMID 32983141, 2020). "We also confirmed no interference of initial bacterial invasion by IL-6 treatment (invasion percentage with and without IL-6 treatments at 1 h post-infection is comparable)." (PMID 32419582, 2020).
infection (continued). "No significant regulation of IL-6 mRNA expression was induced by both mutants and wild type along the entire infection course." (PMID 32064001, 2020). "However, after infection Sting−/− mice showed increased levels of the inflammatory cytokines IL-17, TNF-α, and IL-6 when compared to the WT animals." (PMID 32404867, 2020). "However, TNF-α, IFN-γ, and IL-6 levels were significantly increased in T. cruzi A and BALB/c infected mice when compared with the control groups through the infection." (PMID 33329529, 2020). "Similarly, infection of macrophages with E. coli K1 also induced the secretion of large amounts of TNF-α and IL-6." (PMID 31893612, 2020). "CCL-7, another mediator known to participate in anti-parasitic and infection responses, was upregulated upon MOv18 IgE cross-linking only, while the classical inflammatory mediator IL-6 was not significantly changed." (PMID 33203088, 2020). "While no statistically significant changes occurred with IL-6 or IL-10, both cytokines were correlated over the course of infection." (PMID 32818217, 2020). "After 96 h, 2 and 10 weeks of infection lung leukocytes were obtained from infected AhR−/− and WT mice and analyzed by flow cytometry for the presence of intracellular cytokines (IL-12, TNF-α, IL-1β, IL-6, TGF-β and IL-10) in CD11c+ gated cells." (PMID 32647342, 2020). "Infection with C. albicans led to early upregulation of all factors analyzed in WLA blood, with the exception of IL-1β and IL-6, which were not induced by infection." (PMID 32296424, 2020). "The level of IL-6 mRNA in klotho KO mice was not increased at 1 day post-infection and was decreased at 3 days post-infection." (PMID 33329595, 2020). "In our model, M. haemolytica tended to affect the cell viability of PBECs in the LLI system, which may result in lower TEER values and higher IL-6 and TNF-α release after infection." (PMID 32747652, 2020). "We did not observe any significant differences in the IL-6 serum levels in all test strains during all post-infection periods." (PMID 33109085, 2020). "Since IL-6 and TNF-α are commonly induced immediately after infection, we measured cytokines in plasma at earlier time points (2 and 6 h) after stimulation with S. suis than determined in the in vivo-infection experiment." (PMID 31947746, 2020). "No changes of IL-6 transcription was detected after infection and with TGF-β1-neutralizing antibodies." (PMID 32393780, 2020). "Th-1-type cytokines (IFN-γ, IL-12p70, IL-15, and IL-18) can be over-regulated by infection and proinflammatory cytokines such as TNF-α, IL-1β, IL-6, and IL-21 may participate in the adverse outcomes of pregnancy." (PMID 33343532, 2020). "In the P. gingivalis group, the expression of IL-6 mRNA was restored to the level of the uninfected sample, although a dramatic increase was not induced by infection." (PMID 32244806, 2020). "Interestingly, among the unique upregulated genes upon apical infection of HIBCPP cells, we noted CXCL1, CXCL8 and IL-6." (PMID 32872518, 2020). "Although the frequency of IFNγ-producing CD4+ T cells was significantly reduced in IL-6−/− mice 21 days after Mtb infection, comparable amounts of IFNγ-secreting CD4+ T cells could be detected during the following course of infection." (PMID 33375150, 2020). "In addition, an increase in TNF-α, IL-6, IL-10 and VEGF levels were measured at 6 h and 24 h post infection." (PMID 32316163, 2020). "Similarly, our investigation showed that the decreased levels of TNF-α, IL-6, IL-8 and IL-β in LPS-induced RAW 264.7 and HL-1 cells were inverted after the infection with miR-370-3p inhibitor." (PMID 32414769, 2020).
infection (continued). "Our findings showed significant increases in the levels of IL-6, TNF-α, INF-γ, MCP-1, and NO late in disease progression, which may have contributed to cell death and lymphocytic infiltration at the end of infection." (PMID 32294697, 2020). "Several reports found that the use of IL-6 or CRP were not suitable for diagnosing infection after shoulder arthroplasty, with the sensitivity of both tests less than 50%." (PMID 33008442, 2020). "Similarly, IDO1 showed sixfolds increase, whereas LIF, IL6, CCL2, and VEGF each showed more than threefold increase in expression post infection." (PMID 32546788, 2020). "As such, infection with IAV (strain PR/08) induces secretion of IL-6, IL-8, MIP-1, RANTES, MCP-1, IL-10, and IFN-β, but neither IFN-α nor IFN-γ." (PMID 33255985, 2020). "The levels of CRP and IL-6 can be used for indications of early stage or ruling out the infection without any delay in treatment." (PMID 32316949, 2020). "However, infection was accompanied by the release of significantly enhanced levels of proinflammatory cytokines, including IFN-α2a, TNF-α, IL-6, and GM-CSF (P < 0.001 for each at MOI 1 compared with mock-infected controls)." (PMID 32088771, 2020). "We further studied the degranulation of these cells after contact/infection with ZIKV by measuring β-hexosaminidase release as well as the expression profiles of TNF-α (tumor necrosis factor-α), IL-6 (interleukin-6), IL-10 (interleukin-10) and VEGF (vascular endothelial growth factor)." (PMID 32316163, 2020). "For IL-6 and IL-8, burning and infection with C. albicans had no influence on cytokine release compared to unburned controls indicating that aging of the tissue during the experimental time frame alone leads to increased cytokine release." (PMID 33311597, 2020). "With regard to percent changes for determining the timing of reimplantation, the AUC indicated that percent changes in the CRP (AUC = 0.464), the IL-6 (AUC = 0.534), the ESR (AUC = 0.527), and the fibrinogen (AUC = 0.586) were all poor markers when predicted persistent or recurrent infection." (PMID 32887615, 2020). "Additionally, enhanced production of IL-17, IL-6, and TNF-α were detected in BAL from Sting-/- mice after infection." (PMID 32404867, 2020). "However, HIF-1α can also be stabilized and activated under normoxic conditions in a variety of situations, including contact with inflammatory cytokines (TNF-α, IL-6 and VEGF), exposure to ROS, cyclic mechanical stretch in vitro or by MV in vivo and infection." (PMID 32353952, 2020). "At 12 and 36 h post-infection, no intervendor differences were found in bacterial dissemination, or TNFα and IL-6 levels in the lungs." (PMID 32840685, 2020). "During the process of infection and inflammation, activated mononuclear macrophages or necrotic cells can release a large amount of HMGB1, which can induce the production of TNF-α and IL-6 and other proinflammatory factors." (PMID 32089650, 2020). "Here, we showed that IL-6 is not involved in the control of bacterial replication in macrophages within all analyzed times and infection conditions, indicating that IL-6 is not required for the control of B. abortus replication in IL-6 KO macrophages." (PMID 33322581, 2020). "The resulting iDCs were either infected with HSV-2 strain G or HSV-1 as control, and harvested at 2, 4, 8, or 16 hpi or matured into mDCs, via stimulation with a maturation cocktail, additionally containing IL-1β, IL-6, TNF-α, and PGE2, followed by the same infection procedure as for iDCs." (PMID 31963276, 2020). "Since studies had reported that NH/P68 induced enhanced cytokine gene expression or production in macrophages compared to a virulent isolate, cytokine gene (IL-1β, IL-6, IL-10, IL-12p40, IL-18, TNF-α) expression in moMΦ after NH/68 or 22653/14 infection were monitored over-time." (PMID 32178332, 2020).
infection (continued). "Data from experimental study show IL-6 that arise in ARDS, may have contextual protective or exacerbating roles including severity of infection, survival and tissue remodeling." (PMID 33244382, 2020). "But no reports about IL-6 relating to MP DNA loads and MP infection types in patients with MPP have been found." (PMID 32393186, 2020). "At three days after treatment, amphenmulin could significantly decreased TNF-α, IL-6, and MCP-1 in the serum in comparison to those of the infection group, avoiding the adverse effects of excessive inflammatory factors on wound healing." (PMID 32079232, 2020). "On the other hand, CRP and IL-6 combination displayed excellent specificity and would allow to rule out infection reliably." (PMID 32927683, 2020). "In lung tissues, the TNF-α, IL-1β and IL-6 levels in the positive control group were all significantly higher compared with the negative control group at 72 h after infection." (PMID 33551807, 2020). "To test whether susceptibility could be explained by an overall deficiency in the intestinal immune response we analyzed gene expression for several infection-induced cytokines including TNF, IL-6, S100A, IL-18, and CXCL1." (PMID 32453761, 2020). "Moreover, following intranasal infection with Group A streptococcus, IL-6−/− mice are unable to generate a protective TH17 immune response, indicating that IL-6 is a crucial cytokine for TH17 differentiation also during bacterial infections." (PMID 33375150, 2020). "Studying fever during the natural history of infection is relevant because it is an important and common response and is generated by a number of mechanisms including increases in the concentrations of the inflammatory cytokines, TNF- α and IL-6." (PMID 33306742, 2020). "Moreover, the decreased levels of TNF-α, IL-6, IL-8 and IL-β in LPS+si-NEAT1 group were overturned following infection with anti-miR-370-3p." (PMID 32414769, 2020). "However, infection of AAV6-shRNA-AK149641 resulted in significantly lower expression levels of TNF-α and IL-6." (PMID 32929606, 2020). "Here we found a detrimental increase in Cd4 / Il6 / Il10 expression in heart tissue of BALB/c mice infected with the Y strain, not observed in the absence of SLAMF1, in which Cd8 was increased at the LA phase likely allowing a better control of the infection." (PMID 32925918, 2020). "The infection also increased the IL-6 levels in serum samples of animals non-treated and treated with FeSO4, and showed a trend of being higher in infected DFO-treated animals." (PMID 32295126, 2020). "After 4 h of infection C. diphtheriae strains led to G-CSF secretion of about 750 pg ml−1, while no IL-6 production was measurable." (PMID 31057086, 2019). "Noticeably, PC1 mostly segregated the non-infected vs. infected populations and PC2 distinguished the infection parameters (infection index, percentage of infection, oxidative burst, Elastase, and MPO) vs. the cytokines IL-6, IL-10, IL1-β, and TNF-α production." (PMID 31134162, 2019). "Both F4+ETEC and ETEC-derived flagellin are known to trigger the fast secretion of pro-inflammatory cytokines by porcine IECs at the early stage of infection, such as TNF-α, prostaglandin E2 (PGE2), IL-6, IL-8 and IL-1α, which are intended to disarm or destroy invading bacteria." (PMID 31221216, 2019). "Production of 8 cytokines and chemokines was reduced in mice upon ponatinib treatment at day 5 post-infection, whereas the concentrations of IL-6, IL-10, MCP-1, Eotaxin, IL-12 (p40), and MIP-1β were not affected." (PMID 31293574, 2019). "Therefore, using qPCR, we determined the expression of a variety of cytokines with neutrophil chemotactic properties including IL-6, CCL3, CXCL2 and G-CSF, as well as pro-inflammatory cytokines IL-1β and TNF-α at day 3 (105 PFUs) post-infection." (PMID 30787331, 2019).
infection (continued). "Consequently, we analyzed the mRNA levels of the proinflammatory cytokines TNF-α, IL-1β, and IL-6 and the anti-inflammatory cytokine IL-10, as well as the antimicrobial peptides TAP, DEFB1, and BNBD5 in LEAS-pretreated bMECs before and after infection." (PMID 31612151, 2019). "One big advantage of IL-6 over CRP and PCT is an immediate response to infection." (PMID 31022834, 2019). "The evaluation of the cytokine profile showed that MAYV induces a strong inflammatory response in early days of infection, mediated by cytokines TNF-α, IL-6 and INF-γ and chemokine MCP-1." (PMID 31050676, 2019). "IL-6, IL-8, TNF-α are proinflammatory cytokines, indicating that the LDNs secreted higher proinflammatory cytokines than NDNs upon SFTSV infection, and these might be one of the sources of proinflammatory cytokines in SFTS." (PMID 30717709, 2019). "Indeed, MCC950 treatment induced significant decreases in IL-6 and TNF-α levels on day 1 post-infection and total protein levels on days 3 post-infection (sublethal dose) and 5 post-infection (sublethal and LD50 doses)." (PMID 30964929, 2019). "We also looked at the inflammatory cytokines IL-6, IL-17A and IL-23: IL-6 was expressed in the ganglion cell layer following infection with the PRU parental and mutant strains, but absent with RH parental and knock-out strains." (PMID 30901349, 2019). "IL-6 and IL-8 levels increased significantly compared to BPL-inactivated virus (IL-6: p = 0.0018; IL-8: p < 0.0001) and NC (IL-6: p = 0.0001; IL-8: p < 0.0001) 2 days after infection." (PMID 31068911, 2019). "Nevertheless, a significant increase of interleukin (IL)-6 and interferon (IFN)-γ at 12 h and IFN-β at 24 h post infection in mPSCs implicates that mPSCs might function as a sensor to modulate immune responses to influenza virus infection." (PMID 32038512, 2019). "Interestingly, IL-6, a potent proinflammatory cytokine, was expressed 1.7 times greater in the lungs of WT than NKLAM-/- mice at day 3 post-infection." (PMID 31539400, 2019). "While PM10 exposure had no impact on cell viability or IL-6 production, it did impair IL-8 production both at baseline and in response to NTHi infection." (PMID 31344807, 2019). "The clinical signs, together with the pattern of increased TNF-α, IL-6, IL-12, IL-10 and IL-17 mRNA level observed in BVDV2-infected goat PBMCs in this study, suggested that BVDV-2 induced an acute inflammatory response in the early stage of infection." (PMID 31226933, 2019). "Thus, we examined the expression of IL-1β, IL-6, IL-8, and TNF-α in primary porcine alveolar macrophages (PAMs) during infection." (PMID 31363150, 2019). "Melatonin treatment (30 nM) reduced the levels of IL-6 (2-fold), MCP-1/CCL2 (5-fold), and RANTES/CCL5 (6-fold) compared to vehicle treatment after both 4 and 24 h of infection, while both vehicle and melatonin treatment reduced the levels of IL-10, MIP-2/CXCL2, and KC/CXCL1." (PMID 30949455, 2019). "Although it has been shown that the pro-inflammatory properties of IL-6 can enhance bacteria clearance during infection, mast cell-derived IL-6 does not protect mice from CLP by this mechanism." (PMID 31212724, 2019). "Further, in the absence of IL-6, hRSV-infected mice displayed an increase of lymphocyte recruitment at 7 days post-infection, while neutrophil infiltration was similar to the isotype control." (PMID 30936869, 2019). "Both IL-6 and MIP-1α were significantly elevated as early as day 1 PI and remained elevated through the course of infection suggesting that the pro-inflammatory environment persists for longer periods of time even after plasma viremia levels had declined to levels below the limits of detection." (PMID 31133721, 2019). "BCG/LPS infection significantly enhanced the protein expression of TNF-α and IL-6, as well as the secretion of NO (P<0.05 or P<0.01), and TTEP administration downregulated these proinflammatory biomarkers in the liver of BCG/LPS-induced mice (P<0.05 or P<0.01)." (PMID 31080480, 2019).